TLR4 (toll like receptor 4)
Diseases named in the same sentence as TLR4 in open-access papers (continued):
Sharing a sentence is not in itself a finding about the gene and the disease.
asthma (continued). "Therefore, TLR4 may be one of the targets of Danlong Dingchuan Decoction in treating asthma." (PMID 35186104, 2022). "Compared with the control group, TLR2/TLR4 expression in the lung and duodenum tissues of OVA-induced murine asthma model was increased." (PMID 35911120, 2022). "Toll-like receptors (TLRs) such as TLR4 and TLR2 are important for the adaptive Th2-cytokine-driven inflammatory response in asthma." (PMID 35885021, 2022). "Probiotic and prebiotic treatments reduced the expression of asthma related genes involved in the PI3K/Akt and TLR4/NF‐κB signaling pathways in asthmatic lungs." (PMID 35296330, 2022). "CLCA1 is also one of the 6 genes (CLCA1, IL4, IL13, MMP12, TGFB1, TLR4) found in common between our KE genesets and the genesets proposed by Bosse24 for COPD and Poole27 for asthma." (PMID 33731770, 2021). "The effect of evodiamine treatment protects the asthma, as evodiamine reduces airway inflammation and remodelling in the lung tissue by downregulating the HMGB1/NF-κB/TLR-4 pathway in asthma." (PMID 33577738, 2021). "Lower levels of TLR-4, MyD88, NF-κB, and HMGB1 mRNA in lung tissue were measured in the evodiamine-treated group than in the asthma group." (PMID 33577738, 2021). "In our experiment, the mouse asthma model was successfully replicated, and GAA was used to intervene and detect TLR4/NF-κB-related pathway." (PMID 34037898, 2021). "MiR-146-5p targets inflammatory mediators like COX2, IL-1β, KIT, NFKB1, TLR4, TRAF6, and UHRF1 and has been proposed as a predictor for asthma exacerbations in childhood asthma." (PMID 32998415, 2020). "il-10, il-4, il-13, il-17a, il-2, tlr4, tlr9, ccl2, csf2, and vegfα are top 10 hub nodes in the PPI network, so we inquired the expression profiles of these genes in asthma from the GEO database." (PMID 33133221, 2020). "However, the TLR4 polymorphism was not directly linked to the increased risk for childhood asthma." (PMID 32650475, 2020). "The involvement of neutrophils in severe asthma has been studied and recently, it was reported that HDM via stimulation of TLR4 on neutrophils impairs neutrophil apoptosis." (PMID 29867994, 2018). "IL-33 plays an important role in driving mast cell responses and promoting type-2 allergic inflammation, particularly with respect to asthma, via MyD88-integrated crosstalk amongst the IL-33 receptor (ST2), TLR4 and FcεRI." (PMID 29540770, 2018). "At last the immune blot of the protein extracted from lung tissues demonstrated that paeonol decreased the expression of TLR4 and the nuclear translocation of NF-κB, as well as the phosphorylation levels of P38 and ERK in asthma model." (PMID 30186353, 2018). "Nevertheless, a recent study has been reported that application of TLR2, TLR3, TLR4 and TLR7 agonists all show a protective effect for asthma." (PMID 21364926, 2011). "Here we discuss the current understanding of miRNA involvement in innate immunity, specifically in LPS/TLR4 signalling and in the progression of the chronic inflammatory lung diseases cystic fibrosis, COPD and asthma." (PMID 21029443, 2010). "TLR2 and TLR4 are mostly expressed by immune cells and lung epithelial cells and have major implications in the pathogenesis of chronic lung diseases such as COPD and asthma." (PMID 40468357, 2025). "TLR4, through its TRIF-dependent pathway, can protect against allergic airway disease by modulating CD4+ T cell responses, a function that represents a potential therapeutic target for asthma management." (PMID 40598285, 2025). "In conclusion, this study supports the potential involvement of AKT1, MAPK13, STAT1, and TLR4 in asthma pathogenesis and highlights differences between allergic and nonallergic asthma at the molecular level." (PMID 40650018, 2025). "The previous studies on the interactions between genetic variations in the toll like 4 (TLR4), the main receptor for bacterial endotoxin, and asthma were contradictory as they were underpowered and did not consider different asthma phenotypes." (PMID 40761635, 2025).
asthma (continued). "Similarly, the activation of TLR4 by cockroach allergens results in the release of TSLP, IL-25, and IL-33, further contributing to the inflammatory environment characteristic of asthma." (PMID 39457624, 2024). "The stimulatory effect of eHSP70 on GR expression in asthma and control BEC was mediated by TLR4." (PMID 38641747, 2024). "In addition, the protein expression levels of NLRP3, caspase-1, cleaved caspase-1, GSDMD, GSDMD-N, IL-18, and IL-1β were increased, indicating that MUC1, TLR4/MyD88/NF-κB pathway, and NLRP3-induced pyroptosis are involved in the pathogenesis of asthma." (PMID 37880668, 2023). "The immunosuppressive potential of IMs is nevertheless surpassed by the high dose of the allergens and LPS, given that 100% of WT mice develop asthma upon exposure to high amounts of HDM extracts, a phenomenon that requires Toll-like receptor 4 (TLR4) activation by HDM-borne LPS." (PMID 36776895, 2023). "Furthermore, this study adds to the evidence that MUC1 regulates the TLR4/MyD88/NF-κB pathway and NLRP3 inflammasome-mediated pyroptosis in patients with asthma." (PMID 37880668, 2023). "Therefore, several new drugs targeting different TLRs (TLR3, TLR4, TLR7, TLR8, TLR9) are currently under examination for patients with asthma." (PMID 37759430, 2023). "Consistent with previous records, we also observed that the expression levels of Akt, PI3K, NF-kB, and TLR4 significantly increased in the non-treated asthma group." (PMID 35296330, 2022). "Ibudilast, a nonselective phosphodiesterase 4 (PDE4) inhibitor and TLR4 antagonist, is clinically used to treat asthma." (PMID 34025417, 2021). "According to the data achieved in the present study, on the one hand, the inflammation induced in the murine asthma model could be alleviated by the treatment of YFP, which might be related to the regulatory effect of YFP on the TLR4/NF-κB signaling pathway." (PMID 33542675, 2021). "The expression of HMGB1 and TLR4 mRNAs in 1,25-(OH)2D3 low and middle dose groups was considerably lower than the asthma group and higher than the control one; the high dose group had an augmented expression of HMGB1 and TLR4 mRNAs compared to the asthmatic group." (PMID 28630596, 2017). "We did not observe any association between TLR2, TLR4 or CD14 SNPs and asthma onset, nor was there any modification of these relationships by childhood farm exposure/childhood rural environment." (PMID 28262750, 2017). "We have previously shown that sensitization to OVA performed with TLR4 agonist adsorbed to Alum prevented the development of asthma-like responses without shifting the lung inflammation toward a Th1 pattern." (PMID 28220116, 2017). "We have previously shown that TLR4 agonist (LPS) adsorbed to OVA/alum prevented the development of asthma-like responses via MyD88, but not TRIF pathway." (PMID 26380316, 2015). "Obese and nonobese patients with asthma showed increased percentage of sputum neutrophils, expression of Toll-like receptor 4 (TLR4) mRNA, and suppressed response to bronchodilator after a meal with high content of fat or trans-fat." (PMID 26538828, 2015). "Consistent with this is a previous study in chronic persistent severe asthma (n = 9) which demonstrated increased mRNA expression of the innate immune receptors TLR2, TLR4 and CD14, as well as the cytokines IL-8 and IL-1β in induced sputum from patients with neutrophilic asthma." (PMID 24955983, 2014). "A relationship neither existed for TLR4 rs4986790 or TLR9 rs352140 with asthma when dust or area (rural/urban) was taken into account." (PMID 23496969, 2013). "There was no relation between TLR2 rs5743708 or TLR4 rs4986790 on asthma ever when Eastern or Western environment was taken into account." (PMID 23496969, 2013). "The engagement of TLR2 and TLR4 molecules during house dust mite sensitization leads to an asthma phenotype dominated by neutrophils and TH17 cells, a clinical feature that represent a more severe asthma." (PMID 23805294, 2013).
asthma (continued). "Determination of the TLR4 Asp299Gly/Thr399Ile haplotype is of no clinical benefit in predicting the nature or intensity of cytokine production in children whether currently healthy or among specific at-risk groups characterized by prior infantile broncholitis or current asthma." (PMID 20711470, 2010). "Thus, the reduction of TLR4 by eHSP70 might explain the difference of iHSP70 and iHSP90 in BEC from between COPD and asthma patients." (PMID 38641747, 2024). "Physcion, an anthraquinone derivative, induces DC maturation via TLR4 and promotes the differentiation of Th1 cells without affecting the differentiation of Th2 cells, implying that physcion may be useful for treating asthma with Th1/Th2 cell imbalance." (PMID 39238498, 2024). "Moreover, HMGB1 may be involved in the pathogenesis of asthma by regulating downstream signaling pathways through corresponding receptors and mediates a number of signaling pathways in asthma, such as HMGB1/TLR4/NF‐κB, HMGB1/RAGE, HMGB1/TGF‐β, and so forth." (PMID 38156383, 2023). "The mRNA expressions of TLR4, MyD88, nucleotide-binding oligomerization domain-like pyrin domain-containing protein 3 (NLRP3), caspase-1, interleukin (IL)-18, and IL-1β in induced sputum cells of patients with asthma were upregulated and related to the mRNA expression of MUC1." (PMID 37880668, 2023). "Using the same protocol of S1P-induced asthma-like inflammation, the same authors recently demonstrated that while LPS potentiated S1P-induced AHR, TLR4-defective mice (C3H/HeJ) or BALB/c mice pre-treated with an TLR4 blocking antibody were protected from S1P-induced AHR." (PMID 31191511, 2019). "Now some good inhibitors of TLR4 have been developed, such as TAK-242 and C34, further investigation of these inhibitors on lung eosinophilia may provide new ideas for the prevention and treatment of human asthma." (PMID 31889961, 2019). "Thus, as both LPS/TLR4 and IL-33/ST2 signal via MyD88, there is potential for crosstalk between TLR4 and IL-33R (ST2) on mast cells to promote pathogenesis and exacerbation of asthma." (PMID 29540770, 2018). "Interestingly, in some models, MyD88 molecule appears to be more relevant than TLR4 since MyD88 expression, but not TLR4, was critical for induction of experimental asthma induced by Alternaria extract." (PMID 29867994, 2018). "In light of the fact that TLR4 was essential for ASM growth and the cardinal features of asthma in this model, it is tempting to speculate that disulphide HMGB1/TLR4 interactions are sufficient to induce early life airway remodelling and the development of asthma later in life." (PMID 28099113, 2017). "Since, Treg are required for KSpn-mediated suppression of AAD and TLR4 is required for attenuation of some features of AAD, Treg expression of TLR4 could play a role in KSpn-mediated suppression of AAD and consequently asthma and this requires further investigation." (PMID 27309732, 2016). "TLR2 and TLR4 are expressed by DCs, macrophages, neutrophils, the airway epithelium and some subsets of Tregs, which implicates these cells in many processes that may be manipulated in TLR-directed therapies for AAD/asthma." (PMID 27309732, 2016). "TLR2 and TLR4 are expressed by DCs, macrophages, neutrophils, the airway epithelium and some subsets of Tregs, which implicates them in many cellular processes that may be manipulated in TLR-directed therapies for AAD/asthma." (PMID 27309732, 2016). "In this study we did not try to directly link TLR4 SNPs to clinical outcome, but rather stratified by clinical phenotype (asthma or bronchiolitis) to see if differences might be enriched in these groups." (PMID 20711470, 2010). "We could not show that probiotics can inhibit asthma pathophysiology in absence of TLR4." (PMID 35296330, 2022).
asthma (continued). "Although epidemiological studies demonstrate that high levels of endotoxin exposure may protect against allergen sensitization and inversely correlate with atopic rates, it has not been yet formally determined whether TLR4 stimulation in humans promotes or suppresses asthma." (PMID 29867994, 2018). "However, stratification of children based on current asthma or prior bronchiolitis or the absence of either condition, consistently demonstrates an indistinguishable capacity to express LPS-driven cytokine production between the two TLR4 haplotypes." (PMID 20711470, 2010). "Bronchial chronic bacterial colonization is typically observed in non-T2 severe asthma and COPD patients, including gram-negative bacteria expressing LPS7,30, which activates toll like receptor 4 to promote inflammatory responses of the innate immunity." (PMID 35332239, 2022). "The involvement of TLR2, TLR4 and MyD88 in the pathogenesis of AAD and asthma is incompletely understood, and has not been studied in S. pneumoniae-mediated suppression of AAD." (PMID 27309732, 2016). "However, although drugs targeting TLR4 and CBR1 proteins have been developed, such as TLR4 (Papain and Cyclobenzaprine) and CBR1 (Heptaethylene glycol and Haloperidol), no drugs have been found for treating childhood asthma." (PMID 38730525, 2024). "However, the TLR4 agonist lipopolysaccharide (LPS) induces TLR4 expression rather than that of TLR2 and results in elicitation of asthma." (PMID 35484967, 2022). "Unlike OVA, HDM more closely resembles the human asthma antigen, possesses protease activity, and elicits not only an acquired immune response through major histocompatibility complex (MHC) class II, but also an innate immune response through Toll-like receptor 4 (TLR4)." (PMID 39061887, 2024).
viral infection (195 papers, 2006 to 2025). "The TLR4/MyD88/NF-κB axis has been widely implicated in myocardial inflammation across various conditions, including viral infections." (PMID 41472298, 2025). "VP3, a structural protein of the foot and mouth disease virus (FMDV) is already reported to interact and induce TLR4 to promote viral infection and associated inflammation." (PMID 37153546, 2023). "Direct Calprotectin inhibition was however selected over a TLR4 blocking strategy, as diminished TLR4 activity has long been associated with impaired bacterial and viral infection clearance." (PMID 38094743, 2023). "Further characterization of the mechanisms underlying TLR4 recognition of viral glycoproteins is critical to understand unbalanced inflammatory responses leading to cytokine storm during viral infection." (PMID 36246240, 2022). "Viral proteins as well as host damage-associated molecular patterns, that accumulate following cellular stress during viral infection, were linked to TLR4 activation, with uncontrolled TLR4 activation being associated with severe disease." (PMID 36274722, 2022). "These proteins cause TLR4 activation, to induce an inflammatory response during acute viral infection." (PMID 33505220, 2021). "The studies showed that POPG acts as a competitive ligand for the LPS-binding sites on CD14 and MD2 (the coreceptors for TLR4) and hence inhibit the extensive inflammatory processes associated with those viral infections." (PMID 33505220, 2021). "A protective role of TLR4 has been demonstrated in several other viral infections such as Kaposi’s sarcoma associated herpesvirus (KSHV) or VACV, but several studies confirm that TLR4 can also promote viral expansion, as in the case of MMVT infection." (PMID 34711839, 2021). "In various viral infections, the role of receptors of pathogen-associated pattern molecules like the lipopolysaccharides (LPS) and toll-like receptor 4 (TLR-4) have been implicated in the induction of inflammatory reactions." (PMID 33968808, 2021). "Two sequence variants in the TLR4 gene increased the risk of viral infection, whilst sequence variants in the IL-1Ra gene were associated to a decreased risk of bacterial blood-stream infection (BSI)." (PMID 33339376, 2020). "HMOX1 is further involved in interferon regulation following stimulation of the innate immune receptors TLR3 and TLR4, and has been implicated in various viral infections." (PMID 33163005, 2020). "When comparing the different sequence variants to all the episodes of FN, as well as to the respective MDIs, two sequence variants in TLR4; rs10759931 and rs11536889 were associated with an increased risk of viral infections." (PMID 33339376, 2020). "After that, TLR4 expression in cytoplasm and membrane was determined, and the results showed that viral infection up-regulated membrane-associated TLR4 moderately." (PMID 30419930, 2018). "While TLR4 is the specific signalling receptor for bacterial LPS, recent data suggest a central role for TLR4 signalling in the pathology associated with viral infections." (PMID 28106157, 2017). "For example, Stimforte, a TLR4 activator is approved for the treatment of secondary immuno-deficient states caused by chronic bacterial and viral infections." (PMID 24086587, 2013). "TLR4 signalling has also been linked to several other viral infections including the vesicular stomatitus virus, respiratory syncytial virus, mouse mammary tumor virus and Kaposi sarcoma herpesvirus; however the role of MD2 in these interactions is not clear." (PMID 22428080, 2012). "This does not negate the previous finding that FimH acts as an immune inducer, protecting against viral infection associated with TLR4 and type 1 interferon signaling, but suggests that the mechanisms differ." (PMID 20886096, 2010). "In addition to mediating viral infection and host inflammation, TLR4 has also been found to be associated with autophagic processes." (PMID 39599901, 2024).